BCL2 (BCL2 apoptosis regulator)
Diseases named in the same sentence as BCL2 in open-access papers (continued):
Sharing a sentence is not in itself a finding about the gene and the disease.
cervical carcinoma (continued). "This suggests that MEG3 inhibits cervical cancer progression by regulating PI3K/AKT/Bcl-2/Bax/P21 and PI3K/AKT/MMP-2/9 signaling pathways in cervical cancer." (PMID 36890809, 2023). "The pro-apoptotic effects of pterostilbene were demonstrated in HeLa cervical cancer cells through the ROS-mediated activation of caspase-3 and caspase-9, as well as the downregulation of the antiapoptotic proteins bcl-2 and bcl-xL." (PMID 36675194, 2023). "In this study, downregulated expression of ZNF275 showed a tumor-inhibitory impact on cervical cancer involving a weakening of the AKT/Bcl-2 signaling pathway." (PMID 38067329, 2023). "For example, inhibition of DPP8 expression in cervical cancer cells can inhibit cell proliferation, migration, and invasion by affecting the expression of Bax and BCL2, inhibiting the expression of MMP2 and MMP9." (PMID 36172198, 2022). "Of note, Bcl-2 has been confirmed as a direct target of miR-143 in colon, ovarian, bladder, and cervical cancer 24-26." (PMID 36606191, 2022). "For example, bismahanine, a carbazole alkaloid, exerted anticancer effects on human cervical cancer cells by high Bax/Bcl-2 ratio." (PMID 35164236, 2022). "Overexpression of both Bcl2 and Survivin has been reported in different malignancies, including cervical carcinoma." (PMID 36088372, 2022). "miR-346 also plays a pro-survival role in cervical cancer upon activation of ER stress, reduction of Bcl-2 and release of Beclin-1, induction of autophagy and mitophagy and reduction of ROS and apoptosis." (PMID 35309939, 2022). "Apoptosis induction was accomplished by the activation of caspase-3, 8, which enhances the Bcl-2/Bax ratio and caused the cleavage of the PARP level, whereas it altered the mitochondrial membrane potential in cervix cancer HeLa cells." (PMID 36558146, 2022). "The induction of apoptosis was accomplished by the activation of caspase-3,8 which enhanced the ratio of Bax/Bcl-2 and caused the consequent cleavage of the PARP level, whereas it induced the mitochondrial membrane potential in cervix cancer HeLa cells." (PMID 36558146, 2022). "A recent study indicated that miR-636 suppressed cell survival of cervical cancer by targeting CDK6/Bcl-2." (PMID 33472614, 2021). "In the present study, rutin treatment resulted in increased Bax mRNA level and reduced Bcl-2 mRNA expression levels in cervical cancer SiHa cells." (PMID 34577000, 2021). "AL induces apoptosis of cervical cancer cells through generation of reactive oxygen species, glutathione depletion, and inhibition of Bcl-2/Bax signaling pathway." (PMID 33927214, 2021). "In sum, we have demonstrated that the CANK2A1/HMGA2/Bcl‐2/Bax axis modulates the sensitivity of cervical cancer cells to cisplatin, and potentially provides new therapeutic targets for overcoming chemoresistance in cervical cancer." (PMID 34115920, 2021). "Activation of CHOP elevated the Bax/Bcl-2 ratio and increased ROS production, which induced apoptosis in cervical cancer cells." (PMID 34680171, 2021). "The results thus suggest that miR-300 induces apoptosis in cervical cancer cells by modulating the intracellular levels of caspases and enhancing the Bax/Bcl-2 protein ratio." (PMID 34950207, 2021). "It inhibits proliferation and induces apoptosis on colorectal and cervical cancer cells via caspase activation followed by up- and downregulations of Bax and Bcl-2, respectively." (PMID 34885716, 2021).
cervical carcinoma (continued). "Expression levels of BAX and BCL2 after radiation therapy are useful prognostic markers in patients with human cervical carcinoma." (PMID 34830452, 2021). "Lycopene increases the sensitization of cervical cancer cells to cisplatin via inhibition of cell viability, up-regulation of Bax expression, and down-regulation of Bcl-2 expression." (PMID 32718121, 2021). "The results of the present study showed that cervical cancer cells were inducted for apoptotic cell death by miR-300 via the increase in proapoptotic caspase proteins together with elevation of Bax/Bcl-2 protein ratio." (PMID 34950207, 2021). "The results of the present study along with those from our previous ones, BCL2, HER-2, CD133, CAIX and ERCC1 were revealed to have significant associations with cervical cancer prognosis." (PMID 34350111, 2021). "The aim of this study was to evaluate the predictive value of CD34 and Bcl-2 in the NACT effectiveness of cervical cancer." (PMID 33392721, 2021). "In cervical cancer, the two subtypes of Livin were highly expressed and closely related to clinical stage, and positively correlated with the expression of Bcl-2, indicating that they played a coordinating role in the carcinogenesis of cervical cancer." (PMID 31799193, 2019). "In this study, we also found high levels of Bcl-2 in cervical cancer lesions where RBBP6 expression was low." (PMID 30886526, 2019). "The total saponins isolated and extracted from So. lyratum Thunb exhibited obvious cytotoxicity via induction of apoptosis by decreasing Bcl-2 expression while increasing Bax expression in human cervical cancer Hela cells." (PMID 31354479, 2019). "Previous studies suggested that rhein enhanced the expression of Fas/death-receptor in human cervical cancer Ca Ski cells through the extrinsic pathway and increased the ratio of Bax/Bcl-2 in human aortic smooth muscle cells through the intrinsic pathway." (PMID 29614833, 2018). "Here we conducted a preliminary study to investigate the sensitivity of three cervical cancer cell lines to BH3-mimetic ABT-263 which selectively inhibits BCL-2, BCL-XL and BCL-w and A-1210477, a selective MCL-1 inhibitor." (PMID 29580266, 2018). "Transfection of HMGA2 siRNA decreased HMGA2 mRNA and protein expression, Bcl-2 expression, inhibited cell proliferation, and increased Caspase 3 expression and apoptosis in SiHa, CaSki and S12 cervical cancer cells." (PMID 29487700, 2018). "In our study, we also found that miR-206 down-regulated in cervical cancer tissues from patients, and the expression of c-Met and Bcl2 were up-regulated." (PMID 28615991, 2017). "In 2011, it was reported that ethanol extracts of B. batryticatus possessed significant anti-cervical cancer effect against HeLa cells at concentrations of 3.0–11.0 mg/mL, and anticancer mechanisms may be associated with induction of apoptosis by down-regulating the expression of Bcl-2." (PMID 29053625, 2017). "The up-regulation of Bcl2 and c-Met promotes the cervical cancer’s progress, and the expression of miR-34a and miR-206 significantly correlated with the progression and prognosis in cervical cancer." (PMID 28615991, 2017). "But siRNA-mediated depletion of TFF3 induced the apoptosis of cervical cancer cells by decreasing anti-apoptotic protein, Bcl-2 and increasing pro-apoptotic protein, Bax." (PMID 28070169, 2017). "The activation of caspase-3, caspase-9 and down regulation of Bcl-2 mRNA demonstrated mitochondrial mediated apoptosis in cervical cancer cells, thus delineating brittle star saponin fraction as potent anticancer agents in the treatment of cervical cancer." (PMID 28496480, 2017).
cervical carcinoma (continued). "Based on previous studies which have demonstrated that Bcl2, c-Met are closely related with cervical cancer progression, we found their regulators, miR-34a and miR-206, also play important roles in the development and prognosis of cervical cancer." (PMID 28615991, 2017). "It was reported that miR-143 inhibits tumor proliferation and promotes apoptosis by targeting BCL-2 in cervical cancer." (PMID 28890884, 2017). "We found that α-mangostin effectively inhibited cell viability, resulted in loss of mitochondrial membrane potential (MMP), release of cytochrome C, increase of Bax, decrease of Bcl-2, and activation of caspase-9/caspase-3 cascade in cervical cancer cells." (PMID 28537893, 2017). "This indicates that TUG1 acts as a tumor promoter in cervical cancer by increasing cell proliferation and decreasing cell apoptosis by upregulating Bcl‐2 expression and suppressing the activation of caspase‐3." (PMID 28088836, 2017). "Consistent with previous researches, c-Met and Bcl2 were up-regulated in cervical cancer tissues through immunohistochemistry in our study." (PMID 28615991, 2017). "This indicated that DDP-induced cervical cancer cell apoptosis was enhanced via the down-regulation of Bcl-2 expression and the up-regulation of Bax and caspase-3 expressions." (PMID 29228621, 2017). "In the present study, we investigated the regulation by cisplatin on protein kinase C β (PKC β), on B-cell lymphoma 2 (Bcl-2) and on apoptosis in cervical cancer Hela cells." (PMID 28246354, 2017). "We supposed that the intracellular zinc pools were also decreased in SLC39A7-knockdown cervical cancer cells compared with control, resulting in downregulation of the Bcl-2/Bax ratio, hence allowing acceleration of apoptosis." (PMID 29285013, 2017). "Decreasing the rate of Bcl-2/Bax induces mitochondria-mediated apoptosis in human cervical cancer cells." (PMID 28070169, 2017). "Bax/Bcl-2 is essential for the cell apoptosis process in many cells including cervical cancer cells." (PMID 28545028, 2017). "As target genes of miR-34a and miR-206, Bcl2 and c-Met were up-regulated in cervical cancer tissues through qRT-PCR assay and immunohistochemistry." (PMID 28615991, 2017). "The HDAC inhibitor suberoylanilide hydroxamic acid (SAHA) induces apoptosis in HeLa cervical cancer cells in vitro with bortezomib by activating caspase-3 and increasing the ratio of bax/bcl-2 expression." (PMID 28241481, 2017). "Following treatment of cervical cancer cells, Bax protein was up-modulated and Bcl-2 was down-modulated." (PMID 27586579, 2016). "Our data strongly suggest that utilising a lower dose of cisplatin is feasible when combined with Bcl-2 silencing as an adjuvant treatment, thereby improving both the dose-dependent toxicity, as well as cervical cancer resistance." (PMID 26474854, 2015). "Bcl-2 expression was significantly increased in cervical carcinoma tissue in comparison to normal tissue, LSIL tissue and HSIL tissue." (PMID 26474854, 2015). "In summary, we have demonstrated that in cervical cancer cells, Bcl-2 is up-regulated as a potential means of providing resistance against cisplatin treatment." (PMID 26474854, 2015). "Evidence documenting the expression of Bcl-2 in cervical cancers is confounding, and the role of Bcl-2 under stressful conditions, such as chemotherapy treatment in cervical cancer cells remains poorly understood." (PMID 26474854, 2015). "They found a positive correlation between TLR-8 and Bcl2 or VEGF expression both in cervical cancer tissues as well as HeLa cells." (PMID 25622528, 2015).
cervical carcinoma (continued). "Analysis of the expression profile of Bcl-2 in cervical tissue revealed its up-regulation in cervical carcinoma, which agrees with results obtained from the in vitro data." (PMID 26474854, 2015). "In this study, we found that inhibition of REV3L increased cellular sensitivity to cisplatin with activation of the mitochondrial apoptotic pathway in cervical cancer cells, with altered Bcl-2, Bcl-xl, and Bax expression levels." (PMID 25781640, 2015). "Cisplatin treatment significantly increased Bcl-2 protein levels in both cervical cancer cell lines which was confirmed through immunocytochemistry." (PMID 26474854, 2015). "The upregulation of Bcl-2 in the presence of cisplatin prompted further analysis in order to elucidate its role in cervical cancer survival and its potential interaction with Beclin-1." (PMID 26474854, 2015). "In this study, the GSPs-treated HeLa and SiHa cells were found to express significantly less Bcl-2 protein and more Bak-1 protein than the untreated cells, suggesting that both Bcl-2 and Bak-1 play roles in GSPs-induced apoptosis in cervical cancer cells." (PMID 25187959, 2014). "Our study showed that the overexpression of TROP2 inhibited apoptosis and increased bcl-2 expression, together with decreased bax expression in human cervical cancer cells." (PMID 24086649, 2013). "BCL2 is targeted by miR-143 in cervical cancer, which is involved in apoptosis and tumor formation; miR-1 regulates cardiomyocyte apoptosis by targeting BCL2." (PMID 24079748, 2013). "Apoptotic death induced by 5-aminolevulinic (5-ALA) mediated PDT involved suppression of bcl-2 mRNA levels and elevation of Bax mRNA in cervical cancer cell line and esophageal cancer cell." (PMID 23914299, 2011). "For example, Bcl-2 is commonly overexpressed in a variety of tumour types including cervix carcinoma, and has been shown to bind and sequester Bid to prevent its normal activity." (PMID 15685241, 2005). "Its overexpression in cervical cancer suppressed apoptosis both independently and by increasing Bcl-2 protective activity, which further increased the resistance of cervical carcinoma to the effect of DNA-damaging agents." (PMID 15857509, 2005). "Further mechanistic studies revealed that berberine, the primary active component of berberine hydrochloride, significantly inhibits the proliferation and migration of cervical cancer HeLa cells by downregulating Bcl-2 expression through the TLR4/NF-κB signaling pathway, thereby promoting apoptosis." (PMID 40260114, 2025). "Functional experiments show that interference with IL7R expression can inhibit cervical cancer growth In vitro experiments show that Bcl-2 expression is reduced and caspase-3 expression is increased, which can inhibit cervical cancer growth by promoting apoptosis." (PMID 36890809, 2023). "↑ Apoptosis by ↑ activity of caspase-3, ↑ Bax, and ↓ Bcl-2 protein in cervical cancer cells (HeLa)." (PMID 37762572, 2023).
cervical carcinoma (continued). "In addition, PF mediated caspase-dependent apoptotic cell death by increasing annexin-V-stained cells, measured by flow cytometry, and the expression of Bax and caspase-3 cleavage and downregulating Bcl-2 in the human cervical cancer cell lines HeLa." (PMID 38140352, 2023). "Moreover, the Bax-to-Bcl-2 ratio and caspase-3 activity were increased by amygdalin treatment in HeLa cells, reinforcing the apoptotic effect of amygdalin on cervical cancer cells." (PMID 37762572, 2023). "Additionally, ferulic acid treatment remarkably downregulated the PI3K/AKT, reduced bcl-2 and mcl-1 expression and increased that of bax in Caski cervical cancer cells." (PMID 36675194, 2023). "Moreover, downregulated expression of ZNF275 showed a tumor-inhibitory impact on cervical cancer involving a weakening of the AKT/Bcl-2 signaling pathway." (PMID 38067329, 2023). "In this study, we found that the level of autophagy increased significantly after STAT3 knockout or knockdown in cervical cancer cells by detecting the protein expression levels of Bcl-2 and Beclin-1, it was found that the expression of Bcl-2 decreased, while the expression of Beclin-1 increased." (PMID 35057825, 2022). "In cisplatin resistant cervical cancer cells, the targeting of PARP-1 by miR-7-5p appears to be responsible for the reduction of apoptotic rates that is associated with upregulation of energy production and autophagy through Bcl-2 downregulation." (PMID 35309939, 2022). "After silencing DPP8 in human cervical cancer cell lines, G1 phase arrest increased Bax expression, decreased BCL2 expression, inhibited cell proliferation, promoted cell apoptosis, and inhibited the expression of MMP2 and MMP9, reducing cell migration and invasion." (PMID 36172198, 2022). "In cancer, the silencing of leptin in HeLa cells, a cervical cancer cell line, has reduced the expression of bcl-2 and, consequently, promotes apoptosis and inhibits cell proliferation, thus suggesting the probable role of leptin in the progression of cervical cancer." (PMID 36555171, 2022). "Therefore, the present study focuses on the Bcl-2–Beclin 1 complex and takes RCE-4 as a model drug to deeply clarify the molecular mechanisms underlying its anti-cervical cancer effects." (PMID 34830185, 2021). "However, differences were found between bcl2 expression in the cases with CIN compared with cervical carcinomas." (PMID 34830452, 2021). "Autophagy gene BCL2 can be used as a therapeutic target of some drugs for cervical cancer." (PMID 34257653, 2021). "However, further researches are still required to investigate the roles of CD34 and Bcl-2 in NACT for patients with cervical cancer." (PMID 33392721, 2021). "However, up until now, less study has been dedicated to clarify the association between CD34 or Bcl-2 expression and the response to NACT in cervical cancer." (PMID 33392721, 2021). "Moreover, miR-143 is downregulated in cervical cancer and promotes apoptosis and inhibits tumor formation by targeting BCL-2." (PMID 34681681, 2021). "As for cervical cancer, less study evaluated the predictive value of Bcl-2 expression in NACT." (PMID 33392721, 2021). "Besides, RUSC1-AS1 serves as a ceRNA in cervical cancer by binding with miR-744 and thus increases the expression of the anti-apoptotic protein BCL-2." (PMID 34048366, 2021). "The 5-year survival rate in cervical cancer was also positively correlated with Bcl-2 expression." (PMID 33392721, 2021). "Moreover, TRIM21 degrades anti-apoptotic molecule, Bcl2, thereby triggering apoptosis in cervical cancer cells." (PMID 32678213, 2020). "From in vitro studies, it was found that, after osthole intervention (10 μg/mL, 150 μg/mL, and 200 μmol/L) on HeLa cervical cancer cells, the expression level of Bax m-RNA and Fas was elevated significantly, while the expression level of Bcl-2 mRNA was reduced dramatically." (PMID 32028721, 2020).